CD4 (CD4 molecule)
Diseases named in the same sentence as CD4 in open-access papers (continued):
Sharing a sentence is not in itself a finding about the gene and the disease.
infection (continued). "Remarkably, a drop in miR-181a expression in CD4+ T cells derived from HCV-infected patients boosts DUSP 6 expression and CD4+ T cell dysfunction, suggesting a possible mechanism by which HCV interacts with the cellular immune response to establish infection." (PMID 29669594, 2018). "T CD4+ lymphocytes (Jurkat), monocytes (THP-1) and hepatocytes (HuH-7) cell lineages were infected with OROV at MOI 1 and, at 12 h post infection, infectivity was assessed by immunofluorescence using specific antibodies against OROV proteins and virus-positive cells were counted by flow cytometry." (PMID 29813068, 2018). "Further examination of the tetramer-positive cells revealed that these cells are a heterogeneous population of TCR-βint NK1.1− and NK1.1+ NKT cells and not the TCR-βhiNK1.1+ CD4+ T cells that emerge after infection." (PMID 30374346, 2018). "Our results demonstrate that MALT1 plays an important role in the control of infection by attenuated rabies virus in the CNS of laboratory mice by inducing neuroinflammation and by recruiting and activating CD8+ and CD4+ T cells within the brain in the early phase of infection." (PMID 29367251, 2018). "We also found that some cell types, notably monocytes, T cells, and memory CD4+ T cells, were negative predictors of infection in the Indian cohort." (PMID 30444901, 2018). "However, a significant increase in the number of CD4+ cells was found in the lungs of infected CCR4−/− animals at 15 and 70 days of infection." (PMID 30584243, 2018). "Further characterization of TBEV-specific CD4+ T cell response after an inactivated formalin-inactivated TBEV vaccine (FSME-Immun® 0.5 mL, Baxter, Deerfield, IL, USA) in comparison to the response raised by natural infection were performed." (PMID 30340377, 2018). "Of note, we did not observe any significant difference between groups in the total number of effector CD4 T cells responding to LCMV Cl13 infection, nor in the proportion or total number of IL-21+ single-producing Tfh cells." (PMID 30487586, 2018). "Adoptive CD4+ T cell transfer failed to protect and infection of HCT recipients with no CD8+ T cell transfer was lethal when combined with the depletion of endogenously reconstituted CD8+ T cells." (PMID 30563202, 2018). "Neither diet nor infection significantly affected proportions of CD3+CD4+ helper T cells, CD3+CD8+ cytotoxic T cell populations." (PMID 30473696, 2018). "T-cell activation for these two ECs was as low as measured for 23 HIV-uninfected individuals rather than for 18 HIV progressors at 5 years post-infection (CD4: 1.8% vs 1.5% and 6.8%; CD8: 5.4% vs 3.7% and 22.7%, respectively)." (PMID 29370775, 2018). "Three days post-infection (dpi), flow cytometry was used to measure T-cell proliferation (indicated by decreased CFSE fluorescence intensity; CFSE-low) and HIV infectivity in vector-specific CD4 T cells (intracellular HIV p24+ rate in CFSE-low CD4 T cells)." (PMID 29474461, 2018). "Additionally, the positive correlation in the second blood sample between the albumin/globulin ratio and the CD4/CD8 ratio indicated that both defence systems (humoral and cell-mediated) were engaged because of an infection (predominantly viral)." (PMID 29596432, 2018). "In vitro experiments showed that after direct infection of resting CD4+ T cells a subset of cells with integrated HIV DNA were Gag+ and negative for surface CD4, suggesting internalization and downregulation of CD4." (PMID 29394935, 2018). "Genital mucosal epithelial cells do not express the major HIV-1 receptor CD4 and are normally impervious to infection with the virus." (PMID 29624497, 2018). "Several CD4+ epitopes have been identified in the mouse, including the C57Bl/6 immunodominant epitope, LpnA86−99, which comprises up to 20% of responding CD4+ T cells after LVS infection." (PMID 29682484, 2018).
infection (continued). "A moderate increase in the absolute number of CD4+Foxp3-CD44+GP66 Tet+ T cells frequencies was observed in the IFNARfl/fl x Foxp3YFP-Cre mice on day 46-post infection, but not on day-25 post infection." (PMID 29672594, 2018). "Use of an entry coreceptor, in conjunction with CD4, is the main determinant of HIV/SIV cell targeting, which in turn may be a central factor determining pathogenicity of infection." (PMID 29659623, 2018). "In addition to their direct role in HIV replication and trans-infection, studies by the group of Sharon Lewin revealed the capacity of monocytes and mDC to promote post-integration HIV latency in resting CD4+ T-cells." (PMID 29415518, 2018). "A role for cytolytic infection of OLG was discounted based on the lack of tissue damage in immunodeficient mice, as well as restored myelin loss by transfer of virus specific CD4+ or CD8+ T cells." (PMID 30619363, 2018). "Using the Cm model of chlamydial genital tract infection, we infected wild-type and TLR3-/- mice, and compared the vaginal synthesis of cytokines and chemokines, Chlamydia burden, CD4+/CD8+ T-cell profiles, and genital tract pathology at different time points throughout infection." (PMID 29624589, 2018). "It is likely that this profound role of CD4+ TRM in mediating immunity during HSV-2 infection is due to the location of the infection (genital tract) rather than the viral factors alone." (PMID 30038624, 2018). "When comparing healthy HIV-1 seronegatives (SN), rapid progressors (PR), and NP, we found that monocyte-derived MΦ from NP did not mediate HIV-1 trans infection of autologous CD4+ T cells, in contrast to efficient trans infection mediated by SN and PR MΦ." (PMID 29643243, 2018). "Additionally, CD4+ T cells at lesions express high levels of chemokine receptor type 5 (CCR5), the co-receptor which HIV-1 most commonly uses to establish initial infection." (PMID 29698393, 2018). "ICOS, a co-stimulatory molecule implicated in the induction and maintenance of Tfh cells, was expressed on both NK1.1 positive and negative CD4+ T cells on day 5 after infection." (PMID 30374346, 2018). "However, only the combination of CD4 and CD8 T cells lead to effective control of the infection indicating a cooperative effect of these two cell populations." (PMID 30153311, 2018). "Following infection with HIV-1, both the percentage of infected cells and the amount of p24 released into the cell culture supernatant at day 3 postinfection were significantly reduced in HIF-1α-silenced CD4+ T cells." (PMID 30206166, 2018). "The α4β7 integrin is non-essential for the infection of CD4+ T cells by HIV-1, but can serve as an adhesion receptor that is being increasingly shown to play an important role in HIV-1 pathogenesis." (PMID 30367034, 2018). "Memory CD4 T cell-regulated enhanced inflammatory responses can also be initiated in the absence of infection." (PMID 29992170, 2018). "Moreover, there was a> 25% decrease in the proportion of memory CD4 T cells expressing PD-1, suggesting that the neutralization of PMIF during blood-stage infection reduces memory CD4 T cell exhaustion." (PMID 30006528, 2018). "A well-defined reservoir of HIV-1 is memory CD4+ T cells, where HIV-1 latency is established when an activated CD4+ T cell becomes infected by HIV-1, but transitions to a memory T cell instead of undergoing lytic infection." (PMID 29316955, 2018). "Consistent with this, in our experiment during blood stage PbA infection, ICOS may be involved in the activation of splenic CD4+ and CD8+ T cells as both these cells express significantly higher ICOS." (PMID 29892278, 2018). "We previously reported that the metabolic phenotype of T cell lines after infection with HIV-1 does not reproduce the elevation of glycolysis that is evident in HIV-1 infected primary CD4+ T cells." (PMID 29518929, 2018).
infection (continued). "An ongoing dependence on CD4 T cells for induction and maintenance of virus-specific CD8 bTRM to a persistent CNS infection has clear clinical implications for individuals whose immune status is altered by infection or immunomodulatory therapeutic agents." (PMID 30372487, 2018). "We find that the generation of CD4 memory does not require infection during the effector phase, as activated APC presenting peptides are sufficient to drive in vivo generated CD4 effectors to become memory in uninfected mice." (PMID 29632538, 2018). "In addition, CD4+ T-cell subsets are differentially infected and killed by HIV, thus increasing the complexity of their dynamics during the infection." (PMID 29915583, 2018). "Though these data are consistent with HIV-1 dependency on CD4+ T cell glucose metabolism, a cellular response mechanism to infection cannot be ruled out." (PMID 29518929, 2018). "The decrease in CD4+ cells was observed after primary infection of Eimeria, but not the secondary infection." (PMID 29699573, 2018). "Consistent with the histology shown before, in vivo CD4+ T cell proliferation was not affected during the initial phase of infection." (PMID 30386330, 2018). "As NK cells, the proportion of CD4+ T cells in aged mice was also significantly lower compared to the young mice without infection." (PMID 29896425, 2018). "We hypothesized that persistent L. donovani infection is due to defective expansion of effector CD4+ Th1 cells and IFN-γ-producing CD8+ T cells during the late stage of infection secondary to PD1/PDL-1-mediated immunosuppression or exhaustion." (PMID 29610255, 2018). "A number of recent studies have indicated that CD4 TRM cells established in non-lymphoid tissues after primary infection provide protection against reinfection with the same pathogen." (PMID 30147701, 2018). "In addition to CD4+ IFN-γ+ T cells, increased presence of CD8+IFN-γ+ T lymphocytes were detected in the lungs of DT-treated mice at both post-infection periods." (PMID 30410119, 2018). "On one hand, Tregs suppress HIV-specific effector T-cell responses and are themselves targets of infection, but on the other hand, Tregs suppress HIV-induced immune hyperactivation and thus slow the infection of conventional CD4+ T cells and limit immunopathology." (PMID 29447279, 2018). "This might be due to some kinds of infection in the patient that have decreased the total WBC count and CD4 count as well." (PMID 29732227, 2018). "Notably, significantly fewer mice depleted of both CD4+ and CD8+ T cell subsets resolved the CFT073 infection after 7 dpi, relative to isotype-treated mice." (PMID 30543708, 2018). "We asked whether availability of CD4 T cell help affects recall responses of virus-specific CD8 T cells to MuPyV reinfection and ability to control the challenge infection." (PMID 30372487, 2018). "Further, this report demonstrates for the first time that i.n. vaccination with polyanhydride nanoparticles can induce tissue-resident memory CD4 and CD8 T cells, confer protection against a heterologous virus challenge, and protect against infection in outbred populations." (PMID 30233573, 2018). "Our results demonstrate maintenance of a population of tissue-resident antigen-specific CD4+ T cells up to 52-weeks post-infection, with no measurable decline." (PMID 30097220, 2018). "In YFV-17D-infected conventional NRG-HIS mice, we noticed an overall increase in peripheral CD3+ T cells upon YFV-17D infection without any changes in the ratio of CD4+/CD8+ T cells." (PMID 30487575, 2018). "During chronic HIV infection and in the absence of treatment, abortive infection leads to the release of inflammatory cytokines that contribute to chronic inflammation, CD4+ T cell depletion, dysregulation of T cell homeostasis and ultimately AIDS." (PMID 30352600, 2018).
infection (continued). "Although we were unable to detect differences between CD4+CD25+ between FIV and CO cats in this study, in comparison to SMM infection indicates that IL-10 expression during acute infection may be more relevant to subsequent viral control than IFN-γ." (PMID 29677149, 2018). "However, CD4+ T lymphocytes are the main target of HIV, and after infection, these cells are used by HIV as host to make copies and infect other cells of the body." (PMID 28326304, 2017). "In most of these studies both an increased polyfunctional CD4+ T cell response and vaccine-induced protection in the lung, as measured by decreased CFU in the lung relative to control mice, were observed at the same time point after infection." (PMID 29051764, 2017). "In agreement, studies with mucosal explants from the human reproductive tract, or in non-human primates support the idea that CD4+ T cells are the crucial targets at very early time points of infection." (PMID 29250073, 2017). "Finally, the roles of CD4 and CD8 T cells in inducing IgG antibodies and protective efficacy were investigated after vaccination of CD4 knockout (CD4 KO) and CD8 knockout (CD8 KO) mice during primary and secondary infection." (PMID 29276514, 2017). "In most (but not all) cells, progressive infection accompanies post-transcriptional downregulation of CD4 protein, while surface MHC class I is largely retained." (PMID 28654687, 2017). "Nonetheless, only one mouse of this group died through the infection (right), demonstrating once more that CD4+ T cells are capable of protecting against R. typhi without the capability to produce IFNγ." (PMID 28222146, 2017). "Despite this, some infected children (<1%) maintain stable CD4 counts and remain asymptomatic for more than 7 years of infection [long-term non-progressors (LTNPs)] and their immune activation is low." (PMID 29250072, 2017). "Although GS-9620 was inactive against HIV in purified CD4+ T cells and macrophages, HIV replication was potently inhibited by conditioned medium derived from GS-9620-treated pDC cultures when added to CD4+ T cells prior to infection." (PMID 27799218, 2017). "In IL-6−/− mice, EV-A71 infection increased the numbers of CD4+ T cells and CD8+ T cells, but not the number of CD19+ B cells." (PMID 29233145, 2017). "Immunohistologic examination at day 28 post-aerosol infection revealed that F4/80+ macrophages, CD3+, CD4+ and CD8+ cells localized in perigonadal fat, whereas no positive staining for myeloperoxidase (MPO) abundantly expressed in neutrophils, or for the pan B cell marker B220 was observed." (PMID 29040326, 2017). "In an intradermal infection model, mice infected with a VCP-knockout strain of vaccinia virus had increased numbers of CD4+ and CD8+ T cells at the site of infection, and exhibited increased T-dependent antibody response, compared to infection with the wild-type virus." (PMID 28197139, 2017). "The higher proportion of CD4(+) helper T-cells in affected tonsils was not a consequence of the various infection/pathological scenarios because the paired, contralateral tonsils from PTA-patients harbored the same T-cell numbers, as did tonsils from HY." (PMID 28877231, 2017). "Due to difficulties in infecting resting primary CD4+ T cells in vitro, it will be difficult to establish whether SUN2 has additional cofactor roles in infection." (PMID 29056936, 2017). "Anti-MuHV-4 antibody responses help to contain infection and depend on CD4+ T cells, but a lack of antibody alone does not explain the disease of CD4+ T cell-deficient mice, as B cell-deficient mice survive." (PMID 28394921, 2017). "Indeed, following infection, BAL IAV-specific IgG antibodies, total CD4 T cells and IAV-specific CD8 T cells in the CBFβΔLysM mice were comparable to WT mice." (PMID 28085958, 2017).
infection (continued). "Furthermore, infected children had more phenotypically exhausted PD-1+ CD4+ T cells, more Tregs expressing TNF-RII, and higher IL-10 responses to PfRBCs, which persisted following resolution of infection." (PMID 28821806, 2017). "Analyzing the percentages of TCD8+ in CPT groups at 7 and 14 days after infection, as expected, CPT groups presented lower percentages of CD8+ T cells in relation to CD4+ T cells, but the percentages of CD8+ T cells were higher in infected group in comparison to their control." (PMID 28878763, 2017). "Furthermore, our earlier studies demonstrate that mice vaccinated with exosomes containing mycobacterial antigens can activate both CD4+ and CD8+ T cells and can protect these mice against infection to an extent comparable to M. bovis BCG3." (PMID 28262829, 2017). "Next, we enumerated CD4+ gDT-II and CD8+ gBT-I T cells in the skin 6 days after infection." (PMID 28112242, 2017). "The authors further show that CD4+ T cells develop into TH17 cells in the infection with R. typhi in the absence of IFNγ." (PMID 28770333, 2017). "Following chlamydial genital infection, CXCR3 activates cDC and pDC, and directs them to the infection site and activates CD4 and CD8 T cells into functional subsets, including (not only) Th1 cells, CD8TFN-α T cells." (PMID 29552679, 2017). "Second, we do not know if there were differences in time of infection between the two groups, despite the fact that both groups showed similar time from diagnosis and the mean of CD4+ cells between groups was similar." (PMID 29258550, 2017). "The average CD4+/CD8+ ratio was significantly lower in SLE patients with infection than in those without infection (mean rank, 46.48 vs 66.68, U=692.0, P=0.002)." (PMID 29267496, 2017). "CD4+ T cell-depletion of Zbtb32-/- mice and WT controls prior to infection with clone 13 did not alter the survival of Zbtb32-/- mice, although it did lead to a less severe loss in body weight of both WT and Zbtb32-/- clone 13-infected mice." (PMID 28827827, 2017). "Though it is not clear if those responses are leishmania-specific, deficiency in caspases-1/11 did not affect either GzmB or IFN-γ production by CD8 or CD4 T cells and parasite numbers detected at 5 weeks post-infection remained unchanged." (PMID 28192528, 2017). "Tnfrsf1-dKO CD4+ T cells did not increase in frequency or number following infection, whereas WT CD4+ T cells expanded approximately 15-fold." (PMID 28671989, 2017). "This experimental design allowed a comparison of CD4 T cell reactivity following secondary infection in mice with or without prior H1-specific CD4 T cell memory established." (PMID 28493882, 2017). "Similar to the absolute number of total T cells CD4+ T cells were reduced in the blood of infection groups (not significant)." (PMID 28559930, 2017). "Severe depletion of both CD4+ and CD8+ T-cells characterized the first 10 days of infection." (PMID 28579989, 2017). "Protective DENV immunity, whether through vaccination or natural infection is thought to be comprised of several factors including neutralizing antibody as well as activation of CD8+ and CD4+ T cells." (PMID 28481883, 2017). "MCMV infected mice showed a significant increase of CD4+CD28null T cells in the spleen over time, with a 2-fold increase at day 8 (p < 0.05) and 20-fold increase at day 250 post-infection compared to non-infected mice (d0, p < 0.0001)." (PMID 28386103, 2017). "HIV-1 p24 levels in the supernatants of infected cells were measured at 1, 3, 5 and 7 days post-infection and the results indicated that lenti-X4R5-Cas9 modified primary CD4+ T cells were protected from infection by either X4- or R5-tropic HIV-1 strains, compared to unmodified control." (PMID 28904745, 2017). "Fully immunocompetent C57BL/6 and anti-CD4-treated C57BL/6 mice were markedly protected against reinfection, exhibiting a significant decrease in both bacterial shedding and duration of infection compared to primary infection." (PMID 28739831, 2017).